KDR (kinase insert domain receptor)
Diseases named in the same sentence as KDR in open-access papers (continued):
Sharing a sentence is not in itself a finding about the gene and the disease.
melanoma (186 papers, 2004 to 2026). A malignant, usually aggressive tumor composed of atypical, neoplastic melanocytes. "Despite the uncertain geminal significance of the KDR p.(Gln472His) variant in melanoma tissue, its presence is correlated with increased microvessel density compared with that in patients without the variant." (PMID 38409377, 2024). "We previously reported on the high incidence of germline variant KDR Q472H in a cohort of more than 1000 melanoma patients and its association with increased microvessel density in human tissues." (PMID 38201446, 2023). "This study provides evidence that the KDR Q472H germline variant drives a more aggressive tumor phenotype by promoting the proliferation of human melanoma tumor cell lines as shown and independently validated in TCGA data and murine models." (PMID 38201446, 2023). "Of note, it will also be interesting to associate germline variation in KDR with melanoma susceptibility." (PMID 38201446, 2023). "We previously reported a high incidence of the pathogenic germline variant Q472H in the kinase insert domain receptor (KDR) in melanoma, which was present in 35% of 1223 patients tested." (PMID 38201446, 2023). "MYC amplification was one of the most commonly detected CNVs, other frequent CNVs in mucosal melanoma included NBN and KDR, which were associated with the poor survival of melanoma patients." (PMID 35688842, 2022). "Q472H is frequently observed in melanomas as a germline mutation being associated with increased KDR phosphorylation." (PMID 28957417, 2017). "The KDR p.Q472H germline mutation also confers increased sensitivity to anti-angiogenesis treatment in melanomas." (PMID 29082853, 2017). "First, melanoma patients who harbor the germline variant KDR Q472H have more aggressive tumor biology, as shown by a more proliferative, immunosuppressive phenotype, in addition to being more angiogenic compared to KDR-WT tumors." (PMID 38201446, 2023). "Taken together, our data suggest that the KDR Q472H germline variant may identify a subset of melanoma patients that can benefit from this combination." (PMID 38201446, 2023). "However 37% of tumors contained a (Q472H) mutation in the KDR gene that was previously observed to be a germline mutation in melanomas, non-small cell lung cancers and Ewing sarcomas in association with KDR phosphorylation or microvessel density." (PMID 28957417, 2017). "The KDR variants R1032Q and S1100F were predominantly observed in 11 melanoma patients." (PMID 28743916, 2017). "The KDR p.Q472H variant also appears to play a role in melanoma progression." (PMID 28773588, 2016). "We also examined the impact of KDR-Var on the response of melanoma cells to a combination of VEGFR inhibition with MAPKi." (PMID 38201446, 2023). "Candidate driver events in Triple-WT melanomas include KIT mutations/amplifications and co-amplified RTKs such as PDGFRA and KDR (VEGFR2)." (PMID 33918490, 2021). "Genes where a statistically significant difference in mutation rate was observed were APC (p = 9 × 10−7) in CRC, STK11 (p = 0.008) in NSCLC, and CDKN2A (p = 0.02), ERBB4 (p = 9 × 10−4), FLT3 (p = 0.02), and KDR (p = 0.01) in melanoma." (PMID 28196074, 2017). "In general, we also found that melanoma cell lines express higher levels of KDR than any other lineage in a large collection of cancer cell lines, suggesting a specific cell-autonomous role for KDR in melanoma development." (PMID 26461489, 2015). "While none of the associations of KDR var have been found in the previous extensive GWAS efforts in melanoma, it is unclear if KDR plays a role in melanoma risk." (PMID 38201446, 2023). "The cBioPortal database showed that MYC, NBN and KDR predicted poor survival of melanoma patients." (PMID 35688842, 2022).
melanoma (continued). "Our study revealed that ACTA2 and KDR could be used as responsive markers for PD‐1/PD‐L1 blockade therapy in melanoma." (PMID 34179721, 2021). "Indeed, a trial of cediranib and selumetinib has recently been initiated in solid tumors (NCT01364051) but may be more effective if directed towards melanoma patients with both BRAFV600E mutation and elevated KDR/PDGFRα/β expression." (PMID 26461489, 2015). "Our results suggest that KDR may be a predictive marker of vemurafenib and or MEK inhibitor response and the combination of cediranib and BRAF or MEK inhibitors are an actionable combinatorial regimen for melanoma patients with BRAF mutations." (PMID 26461489, 2015). "The R2cKO mice showed poor angiogenesis in tumors formed by transplantation with sarcoma or melanoma cells, as suggested by decreased tumor weight and decreased expression of endothelial markers, such as PECAM1, VEGFR2/KDR, and VEGF." (PMID 35130955, 2022). "KIT, PDGFRA, KDR, CDK4 and CCND1, MDM2, and TERT amplifications were frequently observed in Triple-WT melanomas." (PMID 34804979, 2021). "In the mouse melanoma xenograft model, similar expression trendy of ACTA2 and KDR genes were observed to that in the clinical dataset." (PMID 34179721, 2021). "Furthermore, we found synergistic interaction between cediranib and PLX4720 in non-melanoma BRAFV600E mutant cell lines with expression of KDR/PDGFRα/β family members, suggesting the combination may be effective broadly across BRAFV600E mutant cancers beyond melanoma." (PMID 26461489, 2015). "In addition, we identified Mesenchyme (COL1A1+), Endothelium (SOX18+, KDR+), proliferating cells (TOP2A+, MKI67+), and some off‐target cells; Glial (MSX1+, SOX2+), Melanoma (PMEL+, PLP1+), and Neuron (DLL3, HES6)." (PMID 35322595, 2022). "We found high expression of tumor cell (as opposed to endothelial or stromal cell) KDR in a number of melanoma patient samples by immunohistochemistry." (PMID 26461489, 2015). "We observed a significant level of caspase 3/7 and 8 activation in PAE/KDR cells, while no caspase activation was detected in the melanoma cells which express little or no VEGFR-2." (PMID 22069683, 2010).
glioblastoma (176 papers, 2009 to 2026). The most malignant astrocytic tumor (WHO grade IV). "It was reported that radioresistance is linked with VEGF-VEGFR-2 (KDR) interplay in glioblastoma cells." (PMID 28225015, 2017). "VEGFC mediates glioblastoma survival, tumorigenicity, and bevacizumab resistance via KDR activation." (PMID 40843133, 2025). "In chromosomal region 4q12, PDGFRA, KIT, and KDR genes are localized, which play critical roles in development of glioblastoma." (PMID 39684714, 2024). "Two patients with MET amplified and PDGFRA/KDR amplified glioblastoma were treated with cabozantinib and attained partial response." (PMID 38143440, 2023). "KDR is upregulated in the tumor vasculature of anaplastic oligodendrogliomas, glioblastoma multiforme, and ependymomas with necrosis, whereas oligodendroglioma, grade II astrocytomas, and anaplastic astrocytomas tend to express weak-to-nondetectable signals." (PMID 37114147, 2023). "Our study supports the feasibility of TTAC-0001 providing therapeutic benefits in glioblastoma and colorectal cancer through inhibitory effects of tumor-associated angiogenesis by preventing VEGF from binding to VEGFR-2/KDR." (PMID 26325365, 2015). "Of most interest was the use of the iCNA algorithm to identify potential novel fusion genes, as was demonstrated in adult glioblastoma with the identification of the KDR:PDGFRA fusion, which we also found in a case of pHGG." (PMID 24548782, 2014). "Coexpression of VEGF and KDR commonly occurs in astrocytoma and glioblastoma cells." (PMID 37114147, 2023). "Furthermore, PPI network analysis demonstrated that AURKA and KDR genes were hub driver genes of glioblastoma." (PMID 31706255, 2019). "The KDR‐PDGFRA fusion is a well‐documented rearrangement, originally described in a 4q12‐amplified glioblastoma and results in the expression of an oncogenic product." (PMID 35545820, 2022). "Molecular profiling of glioblastoma tumors indicates strong expression of VEGF and its receptor, VEGFR-2/KDR." (PMID 26325365, 2015). "The VEGF receptors, VEGFR-1 (flt-1) and VEGFR-2 (KDR), are commonly present on endothelial cells and have also been identified in human glioblastoma cells." (PMID 22295207, 2011). "The first fusion gene found in glioblastoma was the rearrangement located at an amplified region at chromosome 4q12, resulting in the fusing of the kinase domain of PDGFRA with the regulatory domains of KDR (VEGFR2)." (PMID 24548782, 2014). "In glioblastomas (GBM), the most common alterations were gene amplifications (PDGFRA, KIT, KDR, EGFR, and MET) and deletions (CDKN2A and PTEN)." (PMID 27172220, 2016). "For comparison, expression of KDR/VEGFR-2, an angiogenic marker expressed by endothelial cells; CD11b, a monocyte/macrophage marker; and CD45, a pan-leukocyte marker were determined by immunohistochemistry on sequential frozen sections of a glioblastoma used for the in situ hybridization." (PMID 19536297, 2009).
ovarian carcinoma (160 papers, 2008 to 2026). A malignant neoplasm originating from the surface ovarian epithelium. "KDR gene, which encodes vascular endothelial growth factor receptor 2, was shown to promote oncogenic signaling pathways in many different cancers including ovarian cancer." (PMID 34439877, 2021). "ARS also suppresses the secretion of VEGF and its receptor KDR/flk-1, and inhibits microvascular formation in human ovarian cancer." (PMID 39840041, 2024). "Artemisinins were also reported to be able to promote the downregulation of KDR/flk-1 in endothelial and tumor cells, as well as the decrease of human ovarian cancer growth, in an experimental animal model implanted with HO-8910 xenografts." (PMID 34931134, 2021). "The protein expression levels of VEGF and its receptors, Flt-1 and KDR/Flk-1, were detected in 48 cases of ovarian cancer using the streptavidin-biotin complex (SABC) immunohistochemical method, and tumor MVD was evaluated using F8 factor (FVIII-RA)." (PMID 23946799, 2013). "VEGF, Flt-1 and KDR expression was present in the cytoplasm and vessels of the ovarian cancer tissues, exhibited as focal or diffuse expression." (PMID 23946799, 2013). "KDR is a key player in initiating angiogenesis and a drug target in several cancers, including ovarian carcinoma, while VIM is a marker of the epithelial-mesenchymal transition, and there is growing evidence of its involvement in epithelial cancers." (PMID 22548828, 2012). "Vascular endothelial growth factor A (VEGF-A) and its main signaling-receptor VEGFR2 (KDR) are expressed in primary ovarian tumors and autocrine VEGF-A/KDR loop protects ovarian carcinoma cells from anoikis." (PMID 22505926, 2012). "In cancer cells, artemisinins reduce expression of the VEGF receptor KDR/flk-1 in tumour and endothelial cells and slow growth of human ovarian cancer HO-8910 xenografts in nude mice." (PMID 18752857, 2008). "The concentration of mRNA and KDR has been shown in ovarian cancer." (PMID 36835224, 2023). "Similarly, treatment with fucoidan repressed the mRNA expression of angiogenesis related genes including VEGFA, VEGFB, VEGFC, VEGFD, FLT-1, FLT-4, and KDR in the ovarian cancer cells." (PMID 31936539, 2020). "The expression of two other angiogenesis-related genes [i.e., KDR (kinase insert domain receptor) and FLT4 (FMS related tyrosine kinase 4)] was significantly decreased in ovarian cancer cells after treatment with fucoidan and chemotherapeutics." (PMID 37233501, 2023). "The expression of VEGF-A and its receptor (VEGFR2/KDR) in epithelial ovarian cancer facilitated anoikis resistance, and the targeting of VEGF-A using a neutralizing antibody or KDR using a specific inhibitor sensitized the cells to anoikis." (PMID 33854965, 2021). "The present study aimed to investigate the correlation between the expression of vascular endothelial growth factor (VEGF) and its receptors, the Flt-1 and KDR proteins, with clinical pathology and microvessel density (MVD) in ovarian cancer tissue." (PMID 23946799, 2013). "Several reports have identified the VEGFR2, also known as KDR, on epithelial tumour cells, including its localisation in ovarian cancer cells." (PMID 19240722, 2009).
renal cell carcinoma (154 papers, 2008 to 2026). "Axitinib, a small molecule TKI targeting KDR and PDGFR mutations, was FDA-approved for renal cell carcinoma." (PMID 27077911, 2016). "KDR, a pivotal receptor in both vasculogenesis and angiogenesis, processes that are crucial for tumor growth and progression, has been found to exhibit increased expression that correlates with a poor prognosis in renal cell carcinoma." (PMID 38730293, 2024). "A previous study applying immunohistochemistry detected positive staining for KDR in 243 of 262 vascular tumors, but none of the 51 renal cell carcinomas displayed KDR expression." (PMID 39000466, 2024). "VEGFA, KDR, LYN, CD3E and LOX are among those factors that are not identified by DIAMOnD but have a renal cell carcinoma associated literature support." (PMID 29861861, 2018). "Similarly, the receptors VEGFR2 (KDR) and NRP1 were decreased or relatively unchanged in prostate primary tumors while they were up-regulated in renal cell carcinoma (d for prostate, h for kidney)." (PMID 26341082, 2015).
colorectal cancer (147 papers, 2008 to 2026). A primary or metastatic malignant neoplasm that affects the colon or rectum. "In colorectal cancer, for example, a significant association was found between KDR expression, disease stage and lymph status." (PMID 35095996, 2021). "Eleven tagging SNPs in four genes (EFNB2, MMP2, JAG1 and KDR) were significantly associated with overall survival of colorectal cancer patients." (PMID 32751332, 2020). "Studies in colorectal cancer reported association of this SNP in KDR with susceptibility and recurrence, whereas, to the best of our knowledge, no studies using this SNP were conducted in prostate carcinoma patients." (PMID 28143503, 2017). "Previously, we reported that FLT1 SNPs were significantly associated with the hazard of dying of colorectal cancer after diagnosis with colon cancer and KDR SNPs were associated significantly with colorectal deaths after diagnosis with rectal cancer." (PMID 25541970, 2014). "The KDR gene, a significant prognostic marker in colorectal carcinoma, was mutated only in the hypermutated samples." (PMID 24599305, 2014). "Another study showed that higher KDR expression levels afford a very poor prognosis of colorectal cancer." (PMID 37803932, 2023). "Vascular endothelial growth factor (VEGFA) and its receptors 1 fms-related tyrosine kinase 1 (FLT1) and kinase insert domain receptor (KDR) have been newly recognized as critical regulators of angiogenesis and inflammation in colorectal cancer." (PMID 31383782, 2019). "These genes, including HIF1-α, VEGF receptors Flt1 and KDR, and VEGFC, suggest an association of FJX1 and angiogenic gene expression in human colorectal cancer tumor samples." (PMID 23922772, 2013). "The findings indicate that the ability of farrerol to inhibit the proliferation and migration of colorectal cancer cells may be associated with the induction of G0/G1 phase cell cycle arrest and the regulation of VEGF signaling pathway activation via binding to VEGFA and KDR." (PMID 41415563, 2025). "In 60–75% of colorectal cancer cases, high LDH-5expression is strongly correlated with high expression of VEGF-R2 (KDR/Flk-1)." (PMID 27795841, 2016). "KDR, known as a type III receptor tyrosine kinase, is the main mediator of VEGF-induced endothelial activity and is considered as a significant prognostic marker in colorectal carcinoma." (PMID 27077911, 2016).